CUL9 (cullin 9)
Description:
Core component of a Cul9-RING ubiquitin-protein ligase complex composed of CUL9 and RBX1. The CUL9-RBX1 complex mediates ubiquitination and subsequent degradation of BIRC5 and is required to maintain microtubule dynamics and genome integrity. Acts downstream of the 3M complex, which inhibits the ubiquitination of BIRC5. Ubiquitinates apurinic/apyrimidinic endodeoxyribonuclease APEX2. Ubiquitination by the CUL9-RBX1 complex is predominantly mediated by E2 ubiquitin-conjugating enzymes UBE2L3 and UBE2D2.
Synonyms: H7AP1; KIAA0708; PARC
Tractability: PROTAC: UniProt records ubiquitination sites on it; ubiquitination databases record sites on it; its protein half-life has been measured.
Gene: Protein-coding gene on chromosome 6 (43,182,181 to 43,224,587, forward strand). Ensembl gene ENSG00000112659.
Subcellular location: Cytoplasm
Subcellular location (Human Protein Atlas): Cytosol
Pathways (Reactome):
Metabolism of proteins: Neddylation
Gene Ontology:
Molecular function: protein binding; ubiquitin ligase complex scaffold activity; ubiquitin protein ligase activity; ubiquitin protein ligase binding; ubiquitin-protein transferase activity; zinc ion binding
Biological process: microtubule cytoskeleton organization; protein ubiquitination; regulation of mitotic nuclear division; ubiquitin-dependent protein catabolic process
Cellular component: cullin-RING ubiquitin ligase complex; Cul7-RING ubiquitin ligase complex; cytosol; cytoplasm
Genetic constraint (gnomAD): Loss-of-function variants: 78 observed, 281.62 expected, observed/expected ratio (o/e) 0.28, 90% interval 0.23 to 0.33. The upper end of that interval is the gene's LOEUF score, 0.33, which puts it in group 1 of 6, group 1 being the genes least tolerant of losing a copy. Missense variants: 2,531 observed, 3,369.2 expected, observed/expected ratio (o/e) 0.75, 90% interval 0.73 to 0.78. Synonymous variants: 1,186 observed, 1,339.7 expected, observed/expected ratio (o/e) 0.89, 90% interval 0.84 to 0.93.
Homologues: Orthologues: chimpanzee CUL9 (99% identical), macaque CUL9 (98% identical), dog CUL9 (92% identical), pig CUL9 (90% identical), rabbit CUL9 (88% identical), mouse Cul9 (86% identical), rat Cul9 (86% identical), guinea pig CUL9 (84% identical). Paralogues in human: CUL7 (40% identical).
Diseases named in the same sentence as CUL9 in open-access papers:
CUL9 is named in the same sentence as 16 diseases in open-access papers, as found by Europe PMC text mining. Sharing a sentence is not in itself a finding about the gene and the disease. The quoted sentences say what the papers report.
anaplastic ependymoma (1 paper, 2022). Anaplastic ependymoma is a rare, malignant type of ependymoma that most often arises in the supratentorial region of the brain of children and young adults and that manifests with variable symptoms including headaches, nausea, vision impairment, memory loss and difficulty walking. "The mutational profile of the primary tumor and metastases from a patient with recurrent anaplastic ependymoma yielded candidate mediators of metastatic spread, including CUL9 and PIGM." (PMID 36010837, 2022).
breast carcinoma (1 paper, 2025). "In breast cancer, miR-28-5p inhibited breast cancer cell migration through the regulation of WSB2, whereas in colorectal cancer (CRC), reduced expression of CUL9 has been reported to inhibit CRC cell growth." (PMID 41200507, 2025).
colon cancer (1 paper, 2022). "Our results indicated that high CUL9 expression was associated with worse OS in patients with colon cancer." (PMID 36010837, 2022). "In general, high expression of CUL9 was an independent prognostic factor in patients with colon cancer." (PMID 36010837, 2022). "This retrospective study evaluated the clinical implications of CUL9 expression on the prognosis and the predictive value for postoperative adjuvant chemotherapy in consecutive patients with colon cancer." (PMID 36010837, 2022). "A total of 1078 consecutive patients with colon cancer were enrolled and divided into two groups according to CUL9 expression: a high expression group (n = 366) and a low expression group (n = 712)." (PMID 36010837, 2022). "In our results, the prognostic value of CUL9 expression was further confirmed in the external validation cohort that consisted of consecutive patients with colon cancer from France." (PMID 36010837, 2022). "We evaluated the clinical implications of CUL9 expression on the prognosis and the predictive value for adjuvant chemotherapy in colon cancer." (PMID 36010837, 2022). "Because the expression of CUL9 is ubiquitous and high expression has been described in some tumor types, we further researched the clinical phenotype and function of CUL9 expression in colon cancer in this study." (PMID 36010837, 2022). "In this study, we showed that high expression of CUL9 is an independent prognostic factor for OS and DFS in patients with colon cancer." (PMID 36010837, 2022).
neuroblastoma (1 paper, 2021). Neuroblastoma (NB) is the most common solid, extracranial childhood tumor. "We previously reported that CUL9 promotes survival in post-mitotic neurons and neuroblastoma cells." (PMID 33705438, 2021).
ovarian carcinoma (1 paper, 2022). A malignant neoplasm originating from the surface ovarian epithelium.
renal cell carcinoma (1 paper, 2025). "In renal cell carcinoma (RCC), for example, a panel of mRNA markers (CUL9, KMT2D, PBRM1, PREX2, and SETD2) has been identified as a highly accurate classifier, distinguishing RCC from benign renal masses with an AUC of 0.83." (PMID 40149276, 2025).
sarcoma (1 paper, 2018). A usually aggressive malignant neoplasm of the soft tissue or bone. "CUL9 deletion-induced tumorigenesis tends to be organ specific since mice lacking CUL9 were shown to develop tumors in sarcoma, lung, liver, and ovary only." (PMID 29594129, 2018).
sleep disorder (1 paper, 2020). A change from the patient's baseline sleeping pattern, in the hours slept and/or an alteration/dysfunction in the stages of sleep. "GWAS catalog analysis showed a series of previously reported sleep disorder genes, such as MEIS1, CUL9 and FOXP2 40,44,45." (PMID 32332799, 2020).
tumor (8 papers, 2018 to 2026). "The observation that CUL9-deficient mice develop tumours in multiple organs suggests that ubiquitination of phosphorylated kindlin and degradation fails in mitosis, which leads to the mitotic defects and cancer." (PMID 35469017, 2022). "Transcriptomic profiling of TCGA datasets revealed significant up-regulation of CUL1, CUL2, CUL4A, CUL4B, CUL5, CUL7, and CUL9 in tumor tissues, with higher expression correlating with advanced stage and poorer survival, particularly for CUL5 and CUL7." (PMID 42021323, 2026). "CUL9's role in protecting genome integrity and tumor suppression is facilitated by mediating the degradation of survivin and cytochrome C in normal and cancer cells." (PMID 29594129, 2018). "More sequencing data of primary tumors and metastases would permit the identification of the role of CUL9 in tumor progression, including whether it contributes to metastatic potential or even treatment resistance." (PMID 36010837, 2022). "Owing to the positive interaction between CUL9 and activated B cells, CUL9 may enhance the humoral immune response by promoting processes such as activation, proliferation, or antibody secretion of activated B cells, which may affect tumor progression." (PMID 41200507, 2025). "Since MID2 is activated at mitotic exit, we decided to focus our analysis on CUL9 and FBXL10, which have been shown to prevent genome instability, aneuploidy and spontaneous tumour development in cells and mice." (PMID 35469017, 2022).
cancer (7 papers, 2018 to 2026). A tumor composed of atypical neoplastic, often pleomorphic cells that invade other tissues. "While COMMD2, WSB2, and CUL9 have been implicated in various cancers, their roles in LSCC remain underexplored." (PMID 41200507, 2025). "ARHGAP26 and FAM53B were found associated with five cancer types, and PIP5K1C, FBP1, and CUL9 were found to be associated with four cancer types." (PMID 37187613, 2023). "Seven top upregulated emRNAs and related to ccRCC or/and multiple malignant tumors, including CUL9, ATM, ARID1A, KMT2D, PBRM1, PREX2, and SETD2, were selected as candidate biomarkers for further testing." (PMID 36002886, 2022). "Studies at the cellular level, including our own, identified a role for CUL9 in promoting survival in post-mitotic neurons and various cancer cell lines." (PMID 33705438, 2021). "CUL9 promotes ubiquitin mediated proteasomal degradation of cytochrome c in neurons and human brain tumor cell lines, and survivin in human cancer cells." (PMID 33705438, 2021). "Previous studies demonstrated that CUL9 promotes survival in sympathetic neurons and various cancer cells." (PMID 33705438, 2021). "In addition, CUL9-mediated ubiquitination and degradation of Cytc constitute a strategy to alleviate apoptosis under mitochondrial stress in neurons and cancer cells." (PMID 41200507, 2025). "COMMD2, WSB2 and CUL9 contribute significantly to many cancers or tumors." (PMID 41200507, 2025). "New roles for cullins in carcinogenesis will assuredly emerge in the near future since the relationship between cancer and some cullins (i.e., CUL7 and CUL9) is still a relatively new concept." (PMID 29594129, 2018).
cardiovascular diseases (1 paper, 2022). "A genome-wide association study (GWAS) revealed that CUL9 is a risk factor for cardiovascular diseases, but the mechanistic link between CUL9 and cardiovascular diseases remains to be further explored." (PMID 35327608, 2022).
CUL9 also shares sentences with these, for which no sentence is quoted: acute myeloid leukemia (1 paper); Anxiety (1); colorectal cancer (1); lymphoma (1); Parkinson disease (1).